INTS6-AS1 (INTS6 antisense RNA 1)
Gene: Long non-coding RNA gene on chromosome 13 (51,452,364 to 51,554,678, forward strand). Ensembl gene ENSG00000236778.
Gene Ontology:
Biological process: SRP-dependent cotranslational protein targeting to membrane, signal sequence recognition
Cellular component: signal recognition particle, endoplasmic reticulum targeting